COL2A1 (collagen type II alpha 1 chain)
Diseases named in the same sentence as COL2A1 in open-access papers (continued):
Sharing a sentence is not in itself a finding about the gene and the disease.
type II collagenopathies (continued). "Heterozygous mutations in COL2A1 create a spectrum of clinical entities called type II collagenopathies that range from in utero lethal to relatively mild conditions which become apparent only during adulthood." (PMID 27955642, 2016). "Hypochondrogenesis is a type II collagenopathy that is caused by a mutation in the COL2A1 gene located on the long arm of chromosome 12 (locus 12q13.1)." (PMID 26435866, 2015). "Spondyloepiphyseal dysplasia congenita (SEDC, OMIM 183900) is a common subtype of the type II collagenopathies, a heterogeneous group of chondrodysplasias resulting from mutations in the collagen type II alpha-1 gene (COL2A1, OMIM 120140)." (PMID 26030151, 2015). "ANFH is a consequence of impaired blood supply, which is the most typical type II collagenopathy resulting from mutations of the type II collagen gene (COL2A1 OMIM#120140)." (PMID 24949742, 2014). "Thus, the identification of likely pathogenic COL2A1 variants in our patients expands the phenotypic spectrum of type II collagenopathies and suggests that a MASS-like phenotype can be assigned to various hereditary disorders of connective tissue." (PMID 35296718, 2022). "Patients with COL2A1 mutations are collectively called type II collagenopathies." (PMID 27955642, 2016). "COL2A1 mutations can cause type II collagenopathies, some of which include heart and limb defects." (PMID 24476948, 2014). "Recent genetic studies have demonstrated that mutations in the type II collagen gene (COL2A1) may result in certain human disorders collectively termed type II collagenopathies." (PMID 24949742, 2014). "Research on the relationship between COL2A1 and acetabular dysplasia, including case reports and genetic linkage analyses related to hip joint involvement in type II collagenopathies, has shown that COL2A1 is a key player." (PMID 39902299, 2024). "Among the patients in categories 1–3 in this study, pathogenic variants were found in genes such as COL2A1, COMP, and MATN3, which are the causative genes of type II collagenopathy and multiple epiphyseal dysplasia (MED)." (PMID 34122524, 2021). "As dural ectasia and dolichocephaly have not been described in type II collagenopathies, our data expand the clinical spectrum associated with COL2A1 variants." (PMID 35296718, 2022). "Authors of several studies have reported that most mutations that cause type II collagenopathy are distributed in the Gly-X-Y triplet repeats region, and there is no hot spot for mutations in the COL2A1 gene." (PMID 28841907, 2017). "Heterozygous mutations of COL2A1 (OMIM 120140) have been identified in human patients with various rare autosomal dominant conditions characterized by skeletal dysplasia, short stature, and sensorial defects collectively termed as type II collagenopathies." (PMID 27296271, 2016). "Mutations of the C-propeptide of collagen II are a well established cause of type II collagenopathy associated with brachydactyly E; indeed, additional cases of SPD associated to analogous mutations of C propeptide domain of COL2A1 have been previously reported." (PMID 21356074, 2011). "More extensive studies of the COL2A1 including in larger and diverse ethnic groups are warranted to explore the underlying pathogenic mechanism of SEDC and elucidate the potential genotype-phenotype relationship, which in turn may supplement our understanding of type II collagenopathies." (PMID 26030151, 2015). "Despite the wide clinical spectrum of type II collagenopathies, a MASS- or Marfan syndrome-like phenotype associated with COL2A1 variants has not been reported to date." (PMID 35296718, 2022).
spondyloepiphyseal dysplasia congenita (23 papers, 2011 to 2025). A chondrodysplasia characterized by disproportionate short stature, abnormal epiphyses and flattened vertebral bodies. "Different arginine to cysteine mutations in the COL2A1 gene have been described as causing a spectrum of clinical phenotypes, including spondyloepiphyseal dysplasia congenita, spondyloarthropathy, abnormalities in digits and Stickler dysplasia." (PMID 37443051, 2023). "Spondyloepiphyseal dysplasia congenita could be induced by many kinds of variants in COL2A1, most of which resulted in structural changes within the triple‐helical domain of type II collagen." (PMID 31972903, 2020). "For example, an ENU-induced mutation in the collagen 2 alpha 1 (Col2a1) gene has been described to result in spondyloepiphyseal dysplasia congenita (SEDC), with affected mice displaying short humeri, abnormal vertebrae and disorganized growth plates." (PMID 27959934, 2016).
chondrodysplasia (21 papers, 2014 to 2025). "Genetic chondrodysplasias, such as those caused by COL2A1 mutations, offer valuable models for studying the functional roles of specific cartilage zones." (PMID 40564465, 2025). "In this research, COL2A1 was obviously higher in OA and KBD than that in N. Mutations in the COL2A1 have been observed in chondrodysplasia." (PMID 36010590, 2022). "Filtering for variants with high, moderate or low effects according to SNPEff predictions on the protein structure and variants associated with chondrodysplasia-related genes left only one variant within COL2A1 on BTA5 (UMD3.1)." (PMID 29017490, 2017). "These GWAS results support that this COL2A1-associated mutation is very likely a spontaneous germline mutation and chondrodysplasia causing mutations in other genomic and non-coding regions are unlikely." (PMID 29017490, 2017). "The identified spontaneous missense mutation within COL2A1 is most likely the cause of lethal chondrodysplasia in the progeny of Energy P through a dominant negative effect." (PMID 29017490, 2017). "This study provides a first example of a dominant COL2A1 splice site variant as candidate causal mutation of a severe lethal chondrodysplasia phenotype." (PMID 27296271, 2016). "These predominantly glycine to nonserine residue substitutions exclusively create more severe phenotypes like achondrogenesis type II and hypochondrogenesis and correspond to the bovine COL2A1 allele causing chondrodysplasia in Holstein cattle." (PMID 27296271, 2016). "The identified independent spontaneous splice site variant in COL2A1 most likely caused chondrodysplasia and must have occurred during the early foetal development of the sire." (PMID 27296271, 2016). "The phenotypic and genetic findings are comparable to a previously reported COL2A1 missense mutation underlying lethal chondrodysplasia in the offspring of a mosaic French Holstein sire (Igale Masc)." (PMID 27296271, 2016). "Here we report studies in a col2a1 p.Gly1170Ser knock-in mouse model that we constructed to reveal possible mechanisms of how the col2a1 mutation caused chondrodysplasia." (PMID 24475193, 2014). "These phenotypes are similar to the bovine COL2A1-associated chondrodysplasia in Holstein cattle." (PMID 29017490, 2017). "All five available affected calves, their dams and the sire were genotyped by direct sequencing of a targeted PCR product using standard Sanger sequencing in the pedigree for this COL2A1 variant revealing a perfect association of the mutant A allele with the chondrodysplasia phenotype." (PMID 27296271, 2016). "Finally, mutation analysis for chondrodysplasia detected a perfect association between the splice site mutation of COL2A1 and the disease phenotype." (PMID 27296271, 2016). "Our work suggests that the ERS-apoptosis cascade may mediate the col2a1 mutation to cause chondrodysplasia." (PMID 24475193, 2014). "The COL2A1 variants could lead to many forms of chondrodysplasias and cartilage degeneration." (PMID 31972903, 2020). "This syndrome is a congenital form of bovine chondrodysplasia that has been associated with harmful variants in the aggrecan (ACAN) and collagen type II alpha 1 chain (COL2A1) genes." (PMID 40394457, 2025). "Variations in genes encoding cartilage collagens II and XI, COL2A1 and COL11A1, have been associated with chondrodysplasias, which are often associated with Robin sequence, micrognathia, or cleft palate." (PMID 37745857, 2023). "In addition to variants in COL1A1 and COL1A2 associated with OI, many pathogenic variants in COL2A1 and COL10A1 are linked to chondrodysplasias." (PMID 33672767, 2021). "Besides, P.7 carries pathogenic variants in both COL2A1 and COL9A2 mutations resulting in a more severe skeletal deformity and short-trunk dwarfism, while the other two patients (P.16, P.17) in our study only carrying COL9A1/COL9A2 mutation had very mild symptoms, with only mild chondrodysplasia." (PMID 35250876, 2022).
chondrodysplasia (continued). "Our study provides an example of paternal germline mosaicism in cattle as previously reported for achondrogenesis type II COL2A1‐related (OMIA001926‐9913), chondrodysplasia FGFR3‐related (OMIA001703‐9913) and osteogenesis imperfecta COL1A1‐related (OMIA002127‐9913)." (PMID 40525707, 2025). "LOXL3 knockout mice, which was different from COL2A1 and COL11A1 gene mutant mice, presented with spinal deformity but no dwarfism characteristic of chondrodysplasia." (PMID 26307084, 2015).
retinal detachment (19 papers, 2013 to 2025). An eye emergency condition which may lead to blindness if left untreated. "The most prevalent pathogenic genes for high myopia with retinal detachment were Stickler-related genes, including COL2A1 (10.0%, 4/40) and COL11A1 (5.0%, 2/40)." (PMID 40270540, 2025). "Retinal detachment was present in 29 (29/42, 69%) probands, 20 (20/27, 74%) of whom had COL2A1 mutations, and 4 (4/8, 50%) had COL11A1 mutations." (PMID 32756486, 2020). "Missense mutations in COL2A1 were present in six probands, five of which presented with retinal detachment." (PMID 32756486, 2020). "In total, there were five out of six probands with missense COL2A1 mutations that had retinal detachment, whereas 15 out of 21 probands with truncated COL2A1 mutations had retinal detachment." (PMID 32756486, 2020). "In conclusion, we report an atypical phenotype resulting from a novel truncating mutation in the C-propeptide region of COL2A1 with prominent features including short stature, platyspondyly, hip dysplasia, and retinal detachment." (PMID 27955642, 2016). "Additionally, intronic sequence variants affecting the alternative splicing efficiency of exon 2 of COL2A1 have been associated with an increased risk of retinal detachment." (PMID 30568244, 2019). "In addition, Col2a1 previously has been linked with ocular disorders such as retinal detachment." (PMID 35805160, 2022). "Most cases are dominantly inherited through COL2A1/COL11A1 variants encoding type-II/XI collagen, with patients having up to 78% retinal detachment (RD) risk." (PMID 39406934, 2025). "In our study, the majority of patients had a mutant COL2A1 gene, and the incidence of retinal detachments was as high as that reported among Caucasian patients." (PMID 27408751, 2016).
achondrogenesis type II (17 papers, 2014 to 2025). "The significance of this study lies in the identification of a missense mutation in COL2A1 associated with achondrogenesis type II." (PMID 41373627, 2025). "Mutations in the COL2A1 gene, responsible for Achondrogenesis Type II (ACG II), are primarily missense mutations, with glycine substitutions being the most common." (PMID 41373627, 2025). "In conclusion, the pathogenesis of ACG 2, also known as Achondrogenesis Type II, resulting from missense mutations in the COL2A1 gene, involves a complex interplay of defective collagen production, impaired cartilage formation, and cellular stress." (PMID 41373627, 2025). "Achondrogenesis type II (OMIM #200600) is caused by highly disruptive pathogenic variants in the COL2A1 gene, leading to nearly complete failure of cartilage formation and a lethal skeletal phenotype." (PMID 41373627, 2025). "Mutations in the COL2A1 gene have been found to cause achondrogenesis, which is characterized by short arms and legs or other phenotypes that are related to severe skeletal dysplasia." (PMID 39092175, 2024). "Achondrogenesis type II (ACG2) is a lethal skeletal dysplasia caused by dominant pathogenic variants in COL2A1." (PMID 34573377, 2021). "Heterozygous mutations in COL2A1 were found in the other two fetuses (cases 19 and 20) diagnosed with achondrogenesis type II." (PMID 31299979, 2019). "Heterozygous mutations in COL2A1 were found in two fetuses (cases 19 and 20) diagnosed with achondrogenesis type II." (PMID 31299979, 2019). "In addition, 7.9% (3/38) of the fetuses contained variants in COL2A1 that were diagnosed as achondrogenesis, type II." (PMID 36923788, 2023). "Also, mutations in COL2A1 gene result in skeletal abnormalities including the incomplete bone ossification in patients with achondrogenesis type II before birth or the short stature (dwarfism) of patients with Kniest dysplasia." (PMID 29738498, 2018). "Mutations in COL2A1 cause a wide spectrum of skeletal disorders in humans including achondrogenesis type II (ACG2) (OMIM 200610, achondrogenesis, type II; ACG2) which is characterized by short limbs, short ribs, and absence or abnormal ossification of some skeletal parts." (PMID 29017490, 2017).
spondyloepiphyseal dysplasia (17 papers, 2016 to 2025). An osteochondrodysplasia that results in abnormalities of bone growth in the vertebral column and the epiphysis. "The purpose of this study was to describe a family with spondyloepiphyseal dysplasia caused by a novel type II collagen gene (COL2A1) mutation and the family’s phenotypic diversity." (PMID 27274858, 2016). "We described a family with spondyloepiphyseal dysplasia and a novel COL2A1 mutation (c.1349G>C, p.Gly450Ala)." (PMID 27274858, 2016).
hearing loss (15 papers, 2012 to 2025). "In another case (F5/P1), a novel COL2A1 variant (c.1783delG, p.Ala595Leufs*34) classified as likely pathogenic was identified during genetic work-up for hearing loss." (PMID 40727136, 2025). "Only six mutations of COL2A1 gene had been reported to simultaneously cause hearing loss and scoliosis." (PMID 34182999, 2021). "Overall, mutations in COL11A1 (82.5%) and COL11A2 (94.1%) seem to be more frequently associated with hearing impairment than mutations in COL2A1 (52.2%)." (PMID 23110709, 2012). "Some of the tissue specific proteins were found to be involved in pathophysiology of rare, genetic, or syndromic diseases associated with hearing loss, e.g., Collagen type 2 alpha 1 chain (COL2A1) in Stickler syndrome 1 or Myosin heavy chain 9 (MYH9) in various syndromes." (PMID 35573665, 2022). "Mutations in COL2A1 are associated with Stickler syndrome I, STL I, which presents with hearing impairment in about half of the affected patients." (PMID 35573665, 2022). "Several collagen genes (COL1A1, COL1A2, COL2A1, COL4A3, COL4A4, COL4A5, COL11A1, and COL11A2) are associated with hereditary syndromic hearing loss." (PMID 33848312, 2021). "The auditory phenotype associated with mutations in the COL2A1 gene (STL1) is highly variable, with some patients not developing hearing loss, while others present with conductive hearing loss, typically secondary to Eustachian tube problems, as well as sensorineural hearing loss." (PMID 40727136, 2025). "In previous studies, phenotypic diversity was prevalent in COL2A1-related diseases, especially SEDC combined with hearing impairment." (PMID 34182999, 2021).
Kniest dysplasia (14 papers, 2014 to 2025). "Usually, in-frame deletion variants of COL2A1 cause a phenotype such as Kniest dysplasia, which is milder than ACG2." (PMID 34573377, 2021). "Such an instability could well contribute to the disease mechanism in human patients and has been reported to be involved for mutations in COL2A1 causing Kniest dysplasia, in COL3A1 causing Ehlers-Danlos syndrome type IV and in COL17A1 causing junctional epidermolysis bullosa." (PMID 29439465, 2018).
breast cancer (13 papers, 2015 to 2025). A primary or metastatic malignant neoplasm involving the breast. "This in agreement with a previous report documenting a positive association between COL2A1 protein levels and canine mammary tumours development." (PMID 36220861, 2022). "Disease-specific survival discrepancy was observed comparing breast cancer patients of the upper and lower quartile of the collagen family (COL2A1, COL11A1, COL6A1, COL6A2), THBS1 and LUM gene expression signature (log-rank test, P = 0.06)." (PMID 40927672, 2025). "In lung cancer, miR-301 has been reported to target MEOX2, while in breast cancer, it targets COL2A1, PTEN, BBC3, and FOXF2." (PMID 37509289, 2023). "High COL2A1 expression delays the time to recurrence in high-grade plasmacytic ovarian cancer, and upregulation of COL2A1 reduces the migration and invasion of breast cancer cells." (PMID 36553681, 2022). "A recent report also demonstrates a similar upregulation in Col2a1 expression in breast cancer cells." (PMID 32962144, 2020). "The miR-301a-3p had been reported to target MEOX2 in lung cancer, FOXF3, BBC3, PTEN and COL2A1 in breast cancer and RUNX3 in gastric cancer." (PMID 26019136, 2015). "Second, the TCGA BRCA dataset (n = 821) with PAM50 subtypes called by RNAseq was used to validate the differentially expression of COL2A1, COL11A1, COL6A1, COL6A2, THBS1 and LUM among four breast cancer molecular subytpes in an independent cohort." (PMID 40927672, 2025). "MiR-301 is thought to be a breast cancer oncomiR, which promotes tumor invasion and nodal or distant relapses via direct interaction with FOXF2, PTEN, BBC3iso-2, and COL2A1." (PMID 32605588, 2020). "Mechanism dissection indicated that the miR301a promoted breast cancer proliferation and metastasis via targeting FOXF2, BBC3, PTEN, and COL2A1, as well as down-regulated NF-kB-repressing factor and elevated NF-kB activation in human pancreatic adenocarcinoma." (PMID 25940439, 2015). "At the same time, higher expression of 4 important genes (NMU, COL2A1, PRAME, and TTYH1) that contribute to higher breast cancer lung metastasis was observed in the tumors from Black women compared to the tumors from white women with an adjusted p-value of 0.000664734 (one-way ANOVA)." (PMID 36702853, 2023). "Mir-301b targets FOXF2, PTEN, and COL2A1, regulating the proliferation, colony formation, cell migration, invasion, chemotherapy resistance, and tumor growth of ductal invasive breast cancer cells without lymph node metastasis." (PMID 34796198, 2021).
cleft palate (8 papers, 2019 to 2025). Cleft palate is a fissure type embryopathy that affects the soft and hard palate to varying degrees. "Among these genes, Acan and Col2a1 have been identified as causal genes for cleft palate, highlighting a shared genetic basis for two distinct phenotypes—narrow palate and cleft palate—manifesting under different molecular contexts at their onset." (PMID 39925741, 2025). "Specific to skeletal dysplasia, pathogenic variants in genes encoding type II and XI collagen (COL2A1, COL11A1 and COL11A2), Filamin-A (FLNA), and the diastrophic sulfate transport protein (SLC26A2) are all well-known as being associated with cleft palate." (PMID 33446226, 2021). "On the other hand, it has also been found that the COL2A1, COL11A1, and COL11A2 were associated and influence the risk of nonsyndromic forms of cleft palate." (PMID 30924295, 2019). "Previously, two different studies has proposed that major clefting locus might be located at 6p and mutation in several genes such as COL2A1, COL11A1, and COL11A2 caused syndrome that was associated with cleft palate, Robin sequence, and micrognathia." (PMID 30924295, 2019). "As a result, none of Col2a1-Cre; Loxl3f/f embryos had cleft palate." (PMID 40429955, 2025).